PRND (prion like protein doppel)
Description:
Required for normal acrosome reaction and for normal male fertility (By similarity). Can bind Cu(2+).
Synonyms: DPL; dJ1068H6.4; DOPPEL; PrPLP
Tractability: Antibody: UniProt places it where antibodies can reach, with high confidence; its Gene Ontology location is reachable by antibodies, with high confidence; UniProt predicts a signal peptide or a membrane-spanning region.
Gene: Protein-coding gene on chromosome 20 (4,721,909 to 4,728,460, forward strand). Ensembl gene ENSG00000171864.
Subcellular location: Cell membrane
Pathways (Reactome):
Metabolism of proteins: Post-translational modification: synthesis of GPI-anchored proteins
Gene Ontology:
Molecular function: copper ion binding; protein binding
Biological process: acrosome reaction; cellular response to copper ion; single fertilization; protein homooligomerization
Cellular component: external side of plasma membrane; plasma membrane; extracellular region; membrane
Genetic constraint (gnomAD): Loss-of-function variants: 0 observed, 1.51 expected, observed/expected ratio (o/e) 0, 90% interval 0 to 1.55. That is too few expected variants to judge how well the gene tolerates losing a copy. Missense variants: 227 observed, 234.66 expected, observed/expected ratio (o/e) 0.97, 90% interval 0.87 to 1.08. Synonymous variants: 94 observed, 98.2 expected, observed/expected ratio (o/e) 0.96, 90% interval 0.81 to 1.14.
Homologues: Orthologues: chimpanzee PRND (97% identical), macaque PRND (91% identical), pig PRND (80% identical), dog PRND (79% identical), rabbit PRND (77% identical), mouse Prnd (74% identical), rat Prnd (73% identical), guinea pig PRND (68% identical).
Diseases named in the same sentence as PRND in open-access papers:
PRND is named in the same sentence as 12 diseases in open-access papers, as found by Europe PMC text mining. Sharing a sentence is not in itself a finding about the gene and the disease. The quoted sentences say what the papers report.
prion disease (7 papers, 2008 to 2024). A transmissible disease that is caused by a protein that is able to induce abnormal folding of normal cellular proteins, leading to characteristic spongiform brain changes, which are associated with neuronal loss without an inflammatory response. "Cats are a primary host species for FSE, and the highly polymorphic nature we found in the feline PRND gene suggests that PRND polymorphism in cats share genetic characteristics with other prion disease-susceptible animals." (PMID 39682402, 2024). "Among several factors related to prion disease, polymorphisms within the prion-like protein gene (PRND), a member of the prion protein family, have been reported as significantly associated with disease susceptibility in various species." (PMID 38952802, 2024). "The exploration of polymorphisms in the PRND gene of prion disease-resistant species has yielded intriguing findings." (PMID 38952802, 2024). "Genetic factors, particularly polymorphisms in the prion protein gene (PRNP) and prion-like protein gene (PRND), have been linked to prion disease susceptibility in various species." (PMID 39682402, 2024). "In contrast, prion disease-susceptible species, including humans, cattle, sheep, and goats, are highly polymorphic in the PRND gene." (PMID 39682402, 2024). "Previous studies have reported that polymorphisms in the PRND gene are rare in prion disease-resistant species, such as dogs and horses, despite the gene being highly conserved across species." (PMID 39682402, 2024). "This study identifies novel PRND polymorphisms in domestic cats and provides new insights into the genetic factors underlying feline susceptibility to prion diseases." (PMID 39682402, 2024). "Recent case-controlled studies have suggested that susceptibility to prion diseases is associated with PRND polymorphisms at codon 174 and 3′ untranslated region (UTR) +28 in humans, codons 95 and 132 in cattle, codon 26 in sheep, and codon 10 in goats." (PMID 38952802, 2024). "Since the prion-like protein gene (PRND) is known to play a significant role in prion disease susceptibility among the prion protein gene family, investigating the genetic characteristics of the PRND gene in cats is essential." (PMID 39682402, 2024). "Recent studies have reported that the genetic profile of polymorphisms in the PRND gene, a member of the prion protein family, serves as an important cofactor associated with susceptibility to various types of prion diseases." (PMID 38952802, 2024). "Previous studies propose an association between PRND polymorphisms and prion disease susceptibility in several species." (PMID 38952802, 2024). "Previous studies were mainly performed to examine the association between polymorphisms of the PRND gene and prion disease susceptibility." (PMID 30359416, 2018). "The strong LD between PRND and PRNP in this region suggests that PRND polymorphisms may indirectly influence the pathogenicity of prion diseases by altering the structure of PRNP." (PMID 39682402, 2024). "This suggests that PRND SNPs may indirectly contribute to susceptibility to prion diseases across various species." (PMID 38952802, 2024). "In addition, prion disease-resistant animals including dogs and horses showed the weak genetic linkage between the PRNP and PRND genes compared to prion disease-susceptible animals." (PMID 34573540, 2021). "Thus, because of the proximal location and similar structure of the PRNP gene among the prion gene family, the prion-like protein gene (PRND) was noted as a novel candidate gene that contributes to prion disease susceptibility." (PMID 30897750, 2019). "In addition, recent studies have reported a strong linkage disequilibrium (LD) between the PRNP gene and PRND gene in prion disease-susceptible species, sheep and goats." (PMID 30897750, 2019).
prion disease (continued). "Furthermore, we evaluated the LD value between the PRNP gene and the PRND gene in dogs and found relatively weak LD compared to that in prion disease-susceptible animals, such as sheep and goats." (PMID 30897750, 2019). "Among them, the prion-like protein gene (PRND) is a potent candidate gene that may play a role in prion disease susceptibility." (PMID 30897750, 2019). "Particularly, weak linkage between PRNP and PRND SNPs was observed in dogs and horses, which can be interpreted as a characteristic of prion disease-resistant species." (PMID 38952802, 2024). "Several case-controlled studies have confirmed the relationship of the PRND gene with prion disease vulnerability, and strong genetic linkage disequilibrium blocks were identified in prion-susceptible species between the PRNP and PRND genes." (PMID 30897750, 2019). "Previous studies have indicated that prion disease-susceptible species, such as sheep and goats, have a strong LD between the PRNP gene and the PRND gene, which is very interesting." (PMID 30897750, 2019). "Because of the close genomic location and similar structure to PRNP, PRND has been noted as another major candidate gene in prion diseases." (PMID 30359416, 2018). "Additionally, we observed strong linkage between two PRND SNPs, c.97A>G and c.251A>G, and the PRNP InDel c.214_240del within the nonapeptide repeat region, which suggests a potential association with prion disease susceptibility." (PMID 39682402, 2024). "In addition, it is notable that prion disease-resistant animals, including horses and dogs, have a relatively short genetic distance between the PRNP gene and PRND gene compared to prion disease-susceptible animals." (PMID 30897750, 2019). "Thus, the investigation of the genetic characteristics of the PRND gene in dogs as a prion disease-resistant species will be a very important baseline study to obtain clues on the progression of prion disease." (PMID 30897750, 2019). "The important thing is that dogs did not have strong LD between the PRNP gene and the PRND gene, unlike prion disease-susceptible species." (PMID 30897750, 2019). "In recent studies, association studies of prion protein family genes have received attention as a novel view for prion diseases: prion-like protein gene (PRND), prion-related protein gene (PRNT), and shadow of prion protein gene (SPRN) which encode Doppel, Prt, and Shadoo, respectively." (PMID 30359416, 2018). "In goats, a study has been performed to identify prion disease-related SNPs of the PRND gene." (PMID 30359416, 2018). "Although the PRND gene has a significant relationship with prion disease susceptibility and reproductive ability, genetic studies of the caprine PRND gene have not been performed in Korean native black goats thus far." (PMID 30359416, 2018). "To date, no studies have investigated PRND polymorphisms in cats in relation to prion diseases." (PMID 39682402, 2024). "Previous studies have reported weak genetic linkage between the PRND and PRNP genes in prion disease-resistant species, but stronger linkage in prion disease-susceptible species." (PMID 39682402, 2024). "The second, RPSA, is surface ribosomal protein that interacts with laminins (LAM), a dual-specificity phosphatase 18 (DUSP18), and prion protein 2 (PRND), which taken together may suggest various pathological processes such as prion diseases and cancer." (PMID 32624006, 2020). "However, no studies have yet investigated the PRND gene in cats with respect to prion diseases." (PMID 39682402, 2024).
scrapie (5 papers, 2018 to 2024). A fatal disease of the nervous system in sheep and goats, characterized by pruritus, debility, and locomotor incoordination. "Recently, a strong genetic linkage between the PRNP gene and PRND gene was identified, and scrapie-associated SNPs were strictly linked to the genotype of the PRND gene." (PMID 30897750, 2019). "In sheep, the polymorphism at codon 26 of the PRND gene has been shown to correlate with disease susceptibility to scrapie and fertilization trait." (PMID 30359416, 2018). "Notably, previous studies in sheep, a primary host species for scrapie, have shown that sperm production capacity is associated with SNP c.78G>A (A26A) in the ovine PRND gene." (PMID 39682402, 2024). "However, since only 17 scrapie-affected animals were used in that study, the association between polymorphisms of the caprine PRND gene and scrapie was elusive." (PMID 30359416, 2018). "In sheep, linkage disequilibrium (LD) analysis revealed a significant linkage between the G allele of codon 26 of the ovine PRND gene and the ARR allele of the ovine PRNP gene, known to confer genetic resistance to scrapie." (PMID 38952802, 2024). "In a previous study, it was demonstrated that a strong genetic linkage existed in scrapie-associated SNPs between the PRNP and PRND genes in sheep." (PMID 30359416, 2018). "Because goats are another major host of scrapie, we searched for such genetic linkage in the scrapie-associated SNPs among the PRNP, PRND and PRNT genes in Korean native black goats." (PMID 30359416, 2018). "Consequently, the major homozygote genotype of caprine PRND SNPs is genetically associated with the caprine PRNP HH genotype, which is related to scrapie progression." (PMID 38952802, 2024). "Additionally, SNPs c.28T>C, c.151A>G, and c.385G>C in the caprine PRND gene are strongly linked with the SNP c.428A>G (H143R) of the PRNP gene, which is associated with scrapie progression." (PMID 39682402, 2024). "Until now, the causal effect of the PRND and PRNT genes on scrapie susceptibility was unclear because this effect could be induced by an LD block." (PMID 31649311, 2019). "According to case-controlled studies comparing the genetic distribution of PRND gene polymorphisms in codons 26, 56, 132 and 174 and 3’ untranslated region (UTR) +28, these polymorphisms were involved in the susceptibility to scrapie, BSE and sporadic CJD in ruminants and humans." (PMID 30897750, 2019).
Alzheimer disease (2 papers, 2010 to 2022). A progressive, neurodegenerative disease characterized by loss of function and death of nerve cells in several areas of the brain leading to loss of cognitive function such as memory and language. "Earlier onset of Alzheimer's disease: risk polymorphisms within PRNP, PRND, CYP46, and APOE genes." (PMID 21034472, 2010). "Among candidate modifier genes involved in neurological development and functioning, at least four genes are closely related to Alzheimer’s disease including FIS1, DDX39B, PRND, GSTM3." (PMID 36553485, 2022).
astrocytoma (2 papers, 2021). "For instance, an over-expression of the prion-like protein gene PRND (Doppel, Dpl) at both protein and mRNA levels occurs in high-grade astrocytoma and GBM." (PMID 33418999, 2021). "Prion-like protein doppel (PRND), a paralog of the prion (PrP) protein, was upregulated in many malignant diseases, including astrocytomas, osteosarcoma, acute myeloid leukemia, and myelodysplastic syndromes." (PMID 34737762, 2021). "Similarly, Comincini and colleagues found that GBM tumor samples display overexpression in PrPC and prion-like protein Doppel, whilst PRND expression directly relates to tumor malignancy, thus being associated with a worse prognosis in high-grade astrocytoma." (PMID 33418999, 2021).
Infertility (1 paper, 2018). "However, because Doppel protein was mainly expressed in a testis-specific manner, PRND-knockout mice resulted in infertility due to interference of sperm-egg interaction." (PMID 30359416, 2018).
PRND also shares sentences with these, for which no sentence is quoted: tumor (4 papers); cancer (3); acute myeloid leukemia (1); cerebellar degeneration (1); glioma (1); myelodysplastic syndrome (1); osteosarcoma (1).